CTLA4 (cytotoxic T-lymphocyte associated protein 4)
Diseases named in the same sentence as CTLA4 in open-access papers (continued):
Sharing a sentence is not in itself a finding about the gene and the disease.
metastatic melanoma (continued). "The emerging clinical data suggests that a minority of patients with metastatic melanoma (in the range of 10%) achieve durable objective tumor responses when treated with CTLA4 blocking monoclonal antibodies, with most being relapse-free up to 7 years later." (PMID 19457253, 2009). "The anti-CTLA4 blocking antibody tremelimumab increases Th17 cells in peripheral blood of patients with metastatic melanoma." (PMID 19457253, 2009). "Previous studies showed that high CD16 expression, as well as intertumoral CD16+ macrophages levels, are associated with immune-rich tumors and subsequent better prognosis in metastatic melanoma patients treated with anti-PD-1 monotherapy, or in combination with anti-CTLA-4." (PMID 40897819, 2025). "Immune checkpoint inhibitors (ICIs), including those targeting programmed death-1 (PD-1)/programmed death-ligand 1 (PD-L1) and cytotoxic T-lymphocyte protein 4 (CTLA-4), have been used to improve survival in patients with metastatic melanoma, renal cell carcinoma, head and neck cancer, and NSCLC." (PMID 40589698, 2025). "Noteworthy, the Bacillota phylum that elicited Ig responses in the study cohort, was enriched in the baseline fecal microbiota of metastatic melanoma patients, who benefited from the anti-CTLA-4 therapy and more frequently experienced treatment-induced colitis." (PMID 40869383, 2025). "CTLA-4 blockade-based anti-tumor immunity was augmented upon prior vaccination with autologous and irradiated tumor cells engineered to secrete GM-CSF, in patients suffering from metastatic melanoma or ovarian carcinoma." (PMID 38177532, 2024). "Thus, CTLA-4 is an important pharmacological target in the treatment of many neoplastic forms, including metastatic melanoma." (PMID 39086722, 2024). "This study validates the antitumor activity of the combination of pembrolizumab and lenvatinib in real-world patients with metastatic melanoma with confirmed progression on previous anti-PD-1/CTLA-4 therapy and shows for first time the superiority of this combination over chemotherapy." (PMID 39435288, 2024). "Upon further review of the patient’s medical history and prior treatment regimen, it was discovered that he had been receiving immune checkpoint inhibitor (ICI) therapy, specifically nivolumab (a PD-1 inhibitor) and ipilimumab (a CTLA-4 inhibitor), for his metastatic melanoma." (PMID 39553010, 2024). "We evaluated the prognostic value of hypoalbuminemia in context of various biomarkers at baseline, including clinical, genomic, transcriptomic, and blood-based markers, in patients with metastatic melanoma treated with anti-PD-1 monotherapy or anti-PD-1/anti-CTLA-4 combination therapy (n = 178)." (PMID 38755213, 2024). "More than ten years after the approval of ipilimumab, immune checkpoint inhibitors (ICIs) against PD-1 and CTLA-4 have been established as the most effective treatment for locally advanced or metastatic melanoma, achieving durable responses either as monotherapies or in combinatorial regimens." (PMID 37345056, 2023). "To date, ICIs such as the CTLA-4 inhibitor (ipilimumab), the PD-1 inhibitor (nivolumab and pembrolizumab) have been approved by the U.S. Food and Drug Administration for the treatment of metastatic melanoma and have demonstrated significant efficacy." (PMID 37152956, 2023). "This study also found that the IRG risk score we constructed could be stratified according to the sensitivity of CTLA-4 inhibitors in metastatic melanoma." (PMID 37014331, 2023). "Similarly, a separate study identified a patient with metastatic melanoma who demonstrated a partial response to the combination of anti-PD-1 and anti-CTLA-4 therapy but later developed treatment-resistant metastasis with acquired PTEN loss." (PMID 37614504, 2023).
metastatic melanoma (continued). "Dual checkpoint inhibition with CTLA-4 and PD-1 inhibitors has become a well-established therapeutic option for metastatic melanoma with long-term outcomes, yet at the expense of toxicity with more than half of patients receiving ipilimumab and nivolumab having grade 3 or 4 adverse events." (PMID 37484526, 2023). "Importantly, chemokine receptor blockers combined with anti-PD-1 or anti-CTLA-4 antibodies have improved patient survival in metastatic melanoma, a phenomenon, in part, elucidated by our findings." (PMID 36676129, 2023). "Currently, the guidelines suggest the use of ICIs with anti-PD1, in association or not with anti-CTLA4, in patients with metastatic melanoma, regardless of BRAF status, allowing long-lasting responses and long-time survival in the responders." (PMID 37569757, 2023). "In particular, metastatic melanoma and non-small-cell lung cancer are being treated with the use of PD-1 (nivolumab, pembrolizumab, and cemiplimab), PD-L1 (atezolizumab, avelumab, and durvalumab), and CTLA-4 (ipilimumab) blockers." (PMID 37205307, 2023). "In addition, the combination of anti-PD-1 and anti-CTLA-4 has been authorized as a first line therapy for individuals with unresectable or metastatic melanoma, which achieved an objective response rate of 59%." (PMID 37950289, 2023). "For approved immunotherapies, such as PD-1/PD-L1 inhibitors and anti-CTLA-4 agents, treatments are administered until disease progression or unacceptable toxicity, with the exception of metastatic melanoma in complete response for which treatment can be stopped at 6 months." (PMID 37131154, 2023). "While anti-CTLA-4 therapy with the monoclonal antibody ipilimumab has improved the overall survival of metastatic melanoma patients compared to anti-PD-1 therapy, a smaller percentage of patients benefited from anti-CTLA-4 treatment, and more immunotherapy-related adverse events were reported." (PMID 37197667, 2023). "While we were unable to appreciate significant changes in phenotype or bioenergetics, we do demonstrate that TILs derived from patients with CPI-resistant metastatic melanoma retain a type of plasticity that can be influenced by disrupting PD-1 and CTLA-4 interactions." (PMID 37359554, 2023). "As a first-line treatment in metastatic melanoma, anti-CTLA-4 and anti-PD-1 have improved the OS rate of many patients; however, the majority of patients treated with monotherapy are non-responsive, and combinations of anti-PD-1 with anti-CTLA-4 lead to grade III–V adverse events." (PMID 37513949, 2023). "explored the activity of an anti-CTLA-4 antibody in the treatment of metastatic melanoma and found that blocking CTLA-4 resulted in selective depletion of Treg cells within tumor lesions; remarkably, this depletion was dependent on Fcγ receptor-expressing macrophages in the TME." (PMID 36960057, 2023). "Each recurrence was carefully followed-up with extended resection and scheduled treatment using ICIs, nivolumab (anti-PD-1 antibody) 80 mg, and ipilimumab (anti-CTLA-4 antibody) 3 mg/kg intravenously every 3 weeks for a total of 4 doses for aggravated metastatic malignant melanoma." (PMID 36894873, 2023). "In the absence of BRAF mutation, first-line therapy of metastatic melanoma is limited to two options: monotherapy with anti-PD-1 agents (nivolumab or pembrolizumab) or a combination of an anti-PD-1 agent and an anti-CTLA-4 agent (nivolumab and ipilimumab)." (PMID 35911362, 2022). "For this reason, the various options of targeted and immunological therapies such as antibodies against T-lymphocyte-associated protein 4 (CTLA-4, CD152) and programmed death 1 (PD-1) or its programmed death-ligand 1 (PD-L1) are now preferred as first-line therapies for metastatic melanoma." (PMID 35406541, 2022). "In the treatment of metastatic melanoma, radiotherapy combined with anti-CTLA-4 and anti-PD-1 therapy may become a new idea in combined immunotherapies." (PMID 36304470, 2022).
metastatic melanoma (continued). "In the larger cohort of 115 patients treated with anti–CTLA-4 agent for metastatic melanoma, 85% showed an increased chronic and neutrophilic inflammatory infiltrate within the lamina propria, without chronic architectural changes in the majority of cases (61%)." (PMID 35328239, 2022). "Treatment with ipilimumab, a monoclonal antibody targeting CTLA-4, revealed that the clinical success of T cell immune checkpoint antibodies in patients with metastatic melanoma also relies on off-target effects via myeloid-derived suppressor cells expressing CTLA-4." (PMID 36497232, 2022). "Pharmacological inhibition of the MAPK pathway members BRAF and MEK or monoclonal antibodies against immune checkpoint markers CTLA-4 and PD-1 have provided metastatic melanoma patients with previously unattainable opportunities for meaningful and durable responses." (PMID 36497341, 2022). "Anti-CTLA-4 antibodies are clinically active across multiple tumor types, improve OS in metastatic melanoma, and may also enhance T-cell-mediated anti-tumor responses in breast cancer." (PMID 35440655, 2022). "The demonstration of the efficacy of ipilimumab (targeting CTLA-4) in metastatic melanoma and its subsequent regulatory approval in 2011, led to a rapid expansion in the use of ICIs in immunooncology in a number of tumor indications and unprecedented tissue/site-agnostic authorization." (PMID 36700226, 2022). "Although antibodies against CTLA4 and PD-1, used alone or in combination, both can exert a certain curative effect on the unresectable or metastatic melanoma, the clinical benefits remain unsatisfactory owing to the relatively low ORRs and the phenomenon of drug-resistance." (PMID 35265521, 2022). "ICIs that target programmed death protein-1 (PD-1) and cytotoxic T lymphocyte antigen-4 (CTLA-4) have led to substantial improvements in outcomes for patients with metastatic melanoma and have been rapidly employed to reduce recurrences in the resected stage III setting." (PMID 36466880, 2022). "It is now ten years ago that ipilimumab, a monoclonal antibody that interrupts the binding between cytotoxic T-lymphocyte-associated antigen 4 (CTLA-4) and B7, was shown to unleash T-cell activity, improving the overall survival of patients with metastatic melanoma." (PMID 36230620, 2022). "in antibiotically treated mice or germ-free (GF) mice could restore anti-CTLA4 Abs’ therapeutic effect against metastatic melanoma." (PMID 36429112, 2022). "In addition, an increase of Tregs in PBMCs was observed in pancreatic cancer, metastatic renal cell carcinoma, and metastatic melanoma patients following anti-CTLA-4 treatment." (PMID 35326731, 2022). "Moreover, tremelimumab or IgG2 isotype of CTLA-4 antibody has been employed for the treatment of metastatic melanoma, beside ipilimumab which is IgG1 type of anti-CTLA-4 antibody." (PMID 35145371, 2022). "Interestingly, the results showed that systemic butyrate and propionate limit the antitumor effect of anti-CTLA-4 in mice and patients with metastatic melanoma." (PMID 35008915, 2022). "Ipilimumab, which targets cytotoxic T lymphocyte-associated antigen 4 (CTLA-4), and nivolumab and pembrolizumab, which are inhibitors of programmed cell death protein-1 (PD-1), were approved by Food and Drug Administration (FDA) to treat metastatic melanoma." (PMID 36499102, 2022). "Original indications were approved in metastatic melanoma, leading to unprecedented long-term survival outcomes with 5-year overall survival (OS) rates exceeding 50% with combination ipilimumab-nivolumab (anti-CTLA-4 and anti-PD-1)." (PMID 36466880, 2022). "Similarly, anti-PD-L1 along with anti-CTLA-4 and radiotherapy has been demonstrated to promote a better response in a subset of patients with metastatic melanoma." (PMID 35515106, 2022).
metastatic melanoma (continued). "In a phase I clinical study, involving 142 patients with metastatic melanoma, the objective-response rate and progression-free survival have been found significantly higher with ipilimumab (CTLA-4 inhibitor) and nivolumab (PD-1 inhibitor) combined therapy than ipilimumab monotherapy." (PMID 35515106, 2022). "Another phase 1 clinical trial demonstrated an overall response rate (ORR) of 27.3%, which included 2 complete responses and 4 partial responses, in 22 metastatic melanoma patients treated with CD40 agonism (selicrelumab) in combination with anti-CTLA4 (tremilimumab) (NCT01103635)." (PMID 34868044, 2021). "Additionally, in ipilimumab (CTLA-4 antibody)-treated metastatic melanoma patients, there was a greater number of cells expressing intracellular CTLA-4, LAG-3 and TIM-3." (PMID 34575943, 2021). "Previously, we demonstrated that selectively blocking sCTLA-4 boosted antigen-specific immune responses and further, generated effective anti-tumour immunity in the B16F10 model of metastatic melanoma, which was comparable to that achieved with pan-specific anti-CTLA-4 mAb." (PMID 35069536, 2021). "Also, targeting CTLA-4 in patients with metastatic melanomas demonstrates significant development about overall survival." (PMID 33757216, 2021). "A 27-year-old man with metastatic melanoma treated with the combination of an anti-CTLA-4 and an anti-PD1 agent developed steroid-refractory ir-hepatitis and was treated with one cycle of infliximab at the standard dose of 5 mg/kg, achieving the normalization of transaminases." (PMID 34208089, 2021). "Despite the success of immune checkpoint inhibitors that target cytotoxic lymphocyte antigen-4 (CTLA-4) and programmed-cell-death-1 (PD-1) in the treatment of metastatic melanoma, there is still great need to develop robust options for patients who are refractory to first line immunotherapy." (PMID 34944961, 2021). "Finally, the role of soluble CTLA-4 (sCTLA-4) in the identification of irAEs was also investigated in patients with metastatic melanoma (MM) receiving ipilimumab." (PMID 34732257, 2021). "Immunotherapies targeting the immune checkpoint receptors programmed cell death receptor 1 (PD-1) and cytotoxic T-lymphocyte antigen 4 (CTLA-4) have resulted in significantly improved clinical outcomes in patients with metastatic melanoma and are now standard of care treatment." (PMID 34202352, 2021). "Of 235 patients with metastatic melanoma receiving treatment with ICIs at our institution, a total of 167 patients receiving either PD-1 inhibitor alone (pembrolizumab or nivolumab) or in combination with the CTLA-4 inhibitor ipilimumab were included." (PMID 34336290, 2021). "As a result, there have been dramatic improvements in progression-free (PFS) and overall survival (OS), particularly in metastatic melanoma, with 5-years OS rates of over 50 and 44% for those treated with combined anti-CTLA4 and anti-PD1 therapy or anti-PD-1 monotherapy, respectively." (PMID 34291066, 2021). "Indeed, in patients with metastatic melanoma, an anti-CTLA-4 treatment in combination with bevacizumab (an anti-VEGF monoclonal antibody) elicits humoral immunity to Gal-3 and Gal-1; those bi-therapy-treated metastatic patients have improved OS." (PMID 32408492, 2020). "In addition, the combination of PD-1 and CTLA-4 blockade was more effective than either agent alone in metastatic melanoma." (PMID 32256205, 2020). "In particular, several studies showed that the combination of ipilimumab, an anti-Cytotoxic T-lymphocyte Associated Protein 4 (CTLA-4) monoclonal antibody and nivolumab, an anti-Programmed Death 1 (PD-1) monoclonal antibody, leads to improved survival in patients with metastatic melanoma." (PMID 32560298, 2020).
metastatic melanoma (continued). "Since the initial FDA approval of ipilimumab (a CTLA-4 inhibitor) in 2011 for the treatment of metastatic melanoma based on a proven overall survival advantage, antibodies blocking CTLA-4 and PD-1/PD-L1 have been tested and approved across a wide spectrum of malignancies." (PMID 33614492, 2020). "Combination of CTLA-4 and PD-1 blockers was then evaluated to increase the response rates in patients, and the combination of nivolumab plus ipilimumab showed significantly enhance efficacy in metastatic melanoma patients." (PMID 32620130, 2020). "Interestingly, one patient with metastatic melanoma who previously progressed on anti-PD-1 and anti-CTLA-4 checkpoint blockade achieved a fast and durable partial response." (PMID 33182610, 2020). "Furthermore, the combination of ipilimumab (anti-CTLA-4) and nivolumab (anti-PD-1) significantly enhanced efficacy in metastatic melanoma patients." (PMID 33050484, 2020). "Cytotoxic T-lymphocyte-associated protein 4 (CTLA-4) and PD-1 blockade have proven successful in improving survival rates, resulting in the approval of the ipilimumab and nivolumab combination for the treatment of metastatic melanoma and renal cell carcinoma." (PMID 33291555, 2020). "Interestingly, CTLA-4 is not only expressed on the cell surface of T-cells but also found in the serum of metastatic melanoma patients." (PMID 33256089, 2020). "Similarly, the clinical response rate is very low even in patients receiving anti-CTLA4 therapy for unresectable or metastatic melanoma (the first approved indication of anti-CTLA4 therapy)." (PMID 31607934, 2019). "In metastatic melanoma it is known that both anti-CTLA4 and anti-PDL1 treatment failures are driven by a tumor microenvironment full of TNFR2+ Tregs, suggesting that TNFR2 could be a similar escape pathway for the lost effectiveness on current therapies in SS." (PMID 30356161, 2019). "However, it has not yet been clarified how TMB and ctDNA can be used to estimate response to combined CTLA-4 and PD-1 antibody therapy in metastatic melanoma." (PMID 31300034, 2019). "For example, it has been reported that the combination of anti-PD-1 and anti-cytotoxic T lymphocyte antigen 4 (CTLA-4) antibody treatment results in a longer progression-free survival (PFS) than single agent therapy among previously untreated patients with metastatic melanoma." (PMID 31557787, 2019). "Most recently the five-year results from the Phase 3 CheckMate 067 clinical trial for metastatic melanoma showed a five-year overall survival rate of 52% for patients that received dual anti-CTLA-4 and anti-PD-1 therapy compared to 26% and 44% (respectively) for single CPI therapy." (PMID 31771150, 2019). "We analyzed clinical data from patients with metastatic melanoma who were treated with antibodies against CTLA-4, PD-1 or PD-L1, either as single-agent or combination therapy, and identified those who had disease progression in 1 to 3 sites managed with local therapy." (PMID 31340861, 2019). "The efficacy of this strategy was first established in patients with metastatic melanoma based on the antitumor immune response and increased overall survival rates of patients treated with ipilimumab, a monoclonal antibody targeting human CTLA-4." (PMID 30853982, 2019). "Anti-CTLA4 antibody has been used in clinical practice for treating metastatic melanoma." (PMID 30956779, 2019). "In addition, a predictive role of the neutrophils/lymphocytes ratio (N/L) for the clinical efficacy of immune checkpoint blockade was found in a group of metastatic melanoma patients treated with the combination of anti-CTLA-4 mAb and chemotherapy." (PMID 30004433, 2018). "Treatment regimen that includes platinum drugs in combination with immune checkpoint blockers, such as anti-CTLA4 antibody and ipilimumab, has been approved for metastatic melanoma, whereas anti-PD-L1 antibody, atezolizumab, has been approved for metastatic lung cancer." (PMID 29459887, 2018).